MGMT (O-6-methylguanine-DNA methyltransferase)
Diseases named in the same sentence as MGMT in open-access papers (continued):
Sharing a sentence is not in itself a finding about the gene and the disease.
tumor (continued). "MGMT methylation analysis was performed on 68 tumour samples from 65 individual patients including 47 wtGIST (67.7%) and 21 (32.3%) TK mutant (17 KIT and 4 PDGFRA) GIST (30.9%)." (PMID 36198483, 2023). "Segregation of the cohort by tumour MGMT status revealed a less significant and less specific overall survival prediction (p = 0.001)." (PMID 37620410, 2023). "As we know, the MGMT promotor was an important biomarker of tumor response to temozolomide (TMZ) chemotherapy." (PMID 37202742, 2023). "Unfortunately, most GBM are IDH-1 wild type and unmethylated MGMT becomig aggressive and resistant to therapies included the new immune checkpoint inhibitors due to the “cold tumor” phenotype." (PMID 37584750, 2023). "In patients with a MGMT-methylation (O-6-Methylguanine-DNA Methyltransferase methylation) status in the tumour tissue, intensified chemotherapy protocols with addition of lomustine (Chlorethyl-Cyclohexyl-Nitroso-Urea, CCNU) can be applied." (PMID 36796229, 2023). "Recent data suggest that a residual tumour significantly and negatively impacts outcomes even in MGMT-methylated tumours." (PMID 37373988, 2023). "Temozolomide is an oral alkylating agent, which was reported to modulate the tumor resistance through depleting O6-methylguanine-DNA methyltransferase (MGMT) activity." (PMID 36824145, 2023). "In this trial, CPZ has been added to the standard GBM treatment in patients carrying a tumor with a hypo-methylated MGMT gene promoter and thus characterized by resistance to TMZ and poorer prognosis." (PMID 38092755, 2023). "Immunohistochemical detection of MGMT tracked accordingly with known methylated or unmethylated MGMT promoter status assessed from concurrently collected fresh frozen tissue specimens in 3 of the 4 tumor samples." (PMID 37554223, 2023). "As a potential solution, rCBV was able to predict differences in IDH1 mutation and MGMT status, and tissue from hypercellular and hypervascular microfoci revealed greater expression of Ki‐67, HIF‐1a, CD31, and EGFR compared to tumor background." (PMID 36866773, 2023). "We determined that TNT formation enables the exchange of a critical DNA repair enzyme, MGMT, from tumor cells insensitive to TMZ to sensitive cells." (PMID 37476291, 2023). "Efficacy of TMZ therapy depends on the reparative ability of the tumor cells, which is in part controlled by the DNA repair protein MGMT." (PMID 36803465, 2023). "MGMT promoter methylation is related to the increased sensitivity of tumour tissue to chemotherapy with temozolomide (TMZ) and thus to improved patient survival." (PMID 37373988, 2023). "MGMT repairs the DNA damage induced by temozolomide, making patients whose tumours express MGMT resistant." (PMID 37626597, 2023). "The likelihood that the MGMT gene promoter is methylated was greater in tumor tissue compared with control samples (OR = 4.43, 95% CI: 2.85–6.89), indicating that NSCLC frequently has MGMT gene promoter methylation." (PMID 37901797, 2023). "Our model contributes to a definitive mechanistic interpretation but also provides a tool for predicting and rapidly designing new candidates for depleting MGMT activity, including the tumor-targeting MGMT inactivators." (PMID 37631385, 2023). "With the emerging focus on the mechanisms of tumor molecular markers such as IDH1 mutation and MGMT methylation status, new treatment targets and better evidence to guide clinical decision making is a hopeful future." (PMID 37071297, 2023). "A wide variety of potential MGMT inactivators have been designed and synthesized for the purpose of overcoming MGMT-mediated tumor resistance." (PMID 37631385, 2023). "Our established GBM PDX models closely resemble the respective patient’s tumor histology, with similar morphology and expression patterns of MGMT and Ki-67." (PMID 37114125, 2023).
tumor (continued). "This study demonstrated that the number of immune cells infiltrating PAs and MGMT expression were correlated with tumor aggressiveness based on imaging and molecular features." (PMID 36831707, 2023). "Methylation of the MGMT gene promoter reduces the expression of the MGMT protein, allowing increased sensitivity of the tumour tissues to TMZ." (PMID 37373988, 2023). "One study integrated MRI and clinical data (age, gender, weight, and tumor size) to predict tumor genotype of four biomarkers (MGMT, 1q/19q, IDH, and TERT) and OS time." (PMID 36672494, 2023). "The MGMT gene is responsible for a DNA repair enzyme that can help to extricate tumor cells from damage that is induced by alkylating agents." (PMID 37445721, 2023). "Age, MGMT hypermethylation, tumour location and extent of resection were independent prognostic factors." (PMID 36730349, 2023). "In terms of molecular tumor profile, 4 patients (33.3%) had IDH1-mutated tumors and methylation of MGMT gene promoter was observed in 6 patients (50.0%)." (PMID 37245011, 2023). "Another molecular feature of these tumours that is relevant for prognosis is the presence of MGMT promoter methylation." (PMID 37239289, 2023). "MGMT promoter methylation in matched tumor tissue always occurred in conjunction with MGMT promoter methylation in normal tissue." (PMID 37901797, 2023). "Overall, for the 22 patients included in this study, the methylation assays have costed EUR 1320, and the number needed to be tested to find a MGMT-unmethylated tumor was 4.4." (PMID 36826067, 2023). "Methylation of MGMT not only changes the biology of a tumor but also affects its vulnerability to temozolomide." (PMID 36705923, 2023). "These subgroups are determined by DNA methylation analysis, which has been shown increasingly important for tumour classification, subtyping and biomarkers such as 0‐6‐Methylguanine DNA‐methyltransferase (MGMT)." (PMID 35842717, 2022). "Previous non-radiomic studies introduced the role of imaging characteristics in MRI, such as tumor necrosis, enhancement patterns and tumor location, for the prediction of MGMT methylation status." (PMID 36551961, 2022). "The number of patients with tumor recurrence has increased by more than 20%, especially in the subgroup of patients with a methylated MGMT promotor, the subgroup with the highest survival benefit." (PMID 35955454, 2022). "Using non-invasive NIR imaging, this model allowed for a quantitative assessment of MGMT target knockdown and normalization of MGMT expression by tumor volume, measured non-invasively by bioluminescence." (PMID 35406387, 2022). "High levels of MGMT in tumor cells, therefore, induce the formation of a resistant phenotype by reducing the efficacy of alkylating agents such as TMZ, thus leading to therapeutic failure." (PMID 35203272, 2022). "Tumours mapping to meta-topology 3 (temporal neopallial) showed a preference for MGMT promoter methylation." (PMID 36632188, 2022). "In the nomogram, the KPS accounted for the most significant percentage, followed by chemoradiotherapy, age, SII-NLR score, resection extent of the tumor, and MGMT." (PMID 36556130, 2022). "According to the analysis of available TCGA data, 495 tumour samples were hypomethylated, while nine tumour samples were hypermethylated for MGMT." (PMID 35888599, 2022). "In our study, MGMT promoter methylation was a favorable prognostic factor, with the longest survival in younger patients at the time of diagnosis (≤50 years), small tumor (≤32 cm3), and GTR." (PMID 36009577, 2022). "Accordingly, MGMT is more highly expressed in the inner core than in the peripheral area of GBM tumor mass." (PMID 35740330, 2022).
tumor (continued). "Methylation-induced downregulation or silencing of MGMT inhibits its DNA repair mechanism of alkyl group removal, thereby making tumor cells sensitive to cytotoxic alkylating agents like temozolomide which improves patients’ overall survival." (PMID 35180887, 2022). "It relies on the bisulfite conversion of the tumor DNA samples before the PCR amplification of specific CpG dinucleotides within the MGMT promoter region." (PMID 36361838, 2022). "The aim of this study was to determine the optimal cutoff value of MGMT promoter methylation status using volumetric analysis focused on the tumor volume ratio (TVR) measured by MRI." (PMID 35397757, 2022). "Multivariable analysis, with consideration of levetiracetam intake, age at diagnosis, tumor area, intake of dexamethasone, MGMT promoter status, and MIB-1 labeling index, is performed." (PMID 35565263, 2022). "The status of MGMT promoter methylation not only is involved in the inhibition of tumor proliferation but also is related to the anti-tumor effect of TMZ." (PMID 36003766, 2022). "PLMRS was significantly associated with age at diagnosis, tumor grade, IDH mutational status, 1p19q codeletion status, ATRX mutational status, MGMT promoter methylation status, TERT promoter status and histology, but not gender." (PMID 36203434, 2022). "In EAC patients, a significant association was found between CDKN2A, MGMT or TIMP3 promoter hypermethylation and tumor location (p = 0.034, p = 0.0070 and p = 0.013, respectively, Fisher’s exact test)." (PMID 35701814, 2022). "Metabolic volume and tumor/cortex AMT unidirectional uptake ratios were lower in MGMT-methylated tumors." (PMID 35330402, 2022). "Proteomics and in vitro investigations demonstrated that the abundance of SLC38A1 on the plasma membrane is maintained through DSCR3-dependent recycling, resulting in tumor growth and acquired TMZ tolerance in MGMT-deficient GB." (PMID 36613792, 2022). "If cells lack MGMT, O6MeG persists in the tumor cell DNA, which leads to mispairing with thymine and activation of the mismatch repair (MMR) system." (PMID 35565362, 2022). "The chemoresistance caused by the intracellular activity of O6-methylguanine DNA-methyltransferase (MGMT), a DNA repair enzyme reversing the anti-tumor effect of TMZ by specifically removing the methyl group from O6 -positions of guanine residues." (PMID 35982414, 2022). "Patients tended to live longer if they were younger, had surgery, if they had further treatment after surgery (chemo- or radio-therapy), or if they had a tumour marker called MGMT promotor methylation." (PMID 35804940, 2022). "Multivariate analysis showed that the high FABP7 expression, PRS type, tumor grade, age, chemotherapy status, and MGMT methylation status were independently predictive of OS in these patients." (PMID 35783014, 2022). "The results showed that patients sub‐grouped by tumour grade, IDH mutation, 1p/19q codeletion or MGMT promoter unmethylated status, suffer worse outcome in the high‐risk group in TCGA dataset." (PMID 35615996, 2022). "We previously demonstrated that non-ablative radiation improved delivery of anti-MGMT morpholino oligonucleotides (AMONs) to reduce MGMT levels in subcutaneous tumor xenografts." (PMID 33850305, 2022). "In contrast, a greater degree of edema/necrosis and tumor/necrosis volume ratios has been observed in unmethylated MGMT, in agreement with the aggressive nature of these tumors." (PMID 36289752, 2022). "An example of tumour heterogeneity at the epigenetic level occurs with the methylation status of O6-methylguanine-DNA methyltransferase (MGMT)." (PMID 36733367, 2022).
tumor (continued). "The presence of MGMT methylation indicates silencing of the MGMT gene resulting in a reduction in the capability of tumour cells to repair damage from alkylating agents such as temozolomide and confers a better prognosis." (PMID 36434486, 2022). "Valganciclovir was well tolerated and seemed to improve survival after tumor recurrence in patients with recurrent disease both in re-operated and non-re-operated patients and in patients with unmethylated and methylated MGMT promoter status." (PMID 35454863, 2022). "Multivariate analysis treatment-independent variables at diagnosis identified younger age and tumour MGMT promotor methylation to be positive prognostic markers." (PMID 35804940, 2022). "In contrast, tumor purity was higher in tumors with 1p/19q codeletion, IDH1 mutation (R132) and/or MGMT promoter mutation." (PMID 35865015, 2022). "It was shown that overexpression of MGMT and promoter methylation made tumor cells more effective in resisting TMZ drug toxicity, suggesting a close relationship between MGMT and tumor drug chemoresistance and a direct relationship with patient prognosis." (PMID 36457514, 2022). "Tumor-induced edema, an inflammatory response, was a prognostic factor for patients with MGMT promoter methylation." (PMID 36290819, 2022). "Surgery method, MGMT promoter methylation status, IDH mutation status, expression level of Ki67, tumor location, MRI somatotype, postoperative KPS and TMZ cycles were favorable factors for overall survival." (PMID 36483042, 2022). "The MGMT promoter methylation status was positive in 55% of patients with pseudoprogression and in 36% of patients with tumour progression (p = 0.435)." (PMID 36227862, 2022). "We have previously demonstrated the novel use of a non-ablative dose of radiation in combination with IV AMONs to achieve MGMT silencing in radiation primed tumors in a subcutaneous tumor model." (PMID 33850305, 2022). "Six main associations were described: radiogenomic prognosis, MGMT status, IDH, EGFR status, molecular subgroups, and tumor location." (PMID 35330402, 2022). "MGMT expression levels in patient-derived primary tumor cell lines were also found to be downregulated 22–93% by BP." (PMID 35205800, 2022). "TMZ, first-line drug in the treatment of GBM, is effective if the tumor lacks MGMT or expresses the repair protein at a very low level, i.e., <30 fmol/mg protein." (PMID 35565362, 2022). "Multivariate analysis using the Cox proportional hazard model to reveal MGMT promoter methylation status, IDH mutation status, expression level of Ki67, tumor location, MRI somatotype, postoperative KPS and TMZ cycles to be strongly associated with OS." (PMID 36483042, 2022). "MGMT is known to increase the tumor's sensitivity to the alkylating effects of temozolomide and is associated with increased risk of radiation-induced side effects." (PMID 35185410, 2022). "Patients with GBM, especially those with TMZ resistance and those with MGMT positivity, will benefit from this new regimen by targeting multiple anti-tumor mechanisms." (PMID 35346332, 2022). "Firstly, other important tumor-related biomarkers like O6-methylguanine-DNA methyltransferase (MGMT) and telomerase reverse transcriptase (TERT) status that were related to prognosis were not included in the study due to insufficient pathological data." (PMID 35488347, 2022).
tumor (continued). "Scientific studies currently try to overcome these limitations for example by using a compound-drug to increase the alkylating effects in MGMT-expressing tumor tissue." (PMID 35503461, 2022). "Tumor‐derived exosomes contain MGMT gene fusions, which can be utilized as a predictor of tumor recurrence in the patients treated with TMZ." (PMID 36253096, 2022). "The diversity of methods, cut-off values “in the eyes” of researchers, patient- and tumor- heterogeneity, and sizes of cohorts creates discrepancies in MGMT methylation status studies." (PMID 36361838, 2022). "As the methyl group attached to the promoter prevents gene expression, MGMT methylation can be used as a predictive marker of tumor response to chemotherapy involving the application of alkylating agents." (PMID 36289655, 2022). "MGMT hypermethylation, smaller tumor size, and salvage therapy were confirmed to have the most significant positive impact on OS." (PMID 34940951, 2022). "The PuMRS high-risk group significantly had higher tumor grade, more TERT promoter mutation, less IDH mutation, less 1p/19q codeletion, less MGMT promoter methylation, and less ATRX mutation." (PMID 36438805, 2022). "According to each tumor entity, high MGMT hypermethylation was observed in 10 (10%) iCCA, 6 (26%) dCCA, and 13 (38%) of GBC patients." (PMID 35621918, 2022). "Subgroups were divided by the clinical features, including tumor type (primary or recurrent), grade, sex, age, IDH mutation status, 1p/19q codeletion status, and MGMT promoter status." (PMID 36111134, 2022). "The relationship of other clinicopathological features, including tumor grade, histological diagnosis, IDH mutation status, 1p/19q codeletion, TERT promoter status, ATRX status, and MGMT promoter status, with the TrMRS were also given out." (PMID 36386216, 2022). "When evaluating the OS of patients with GBM, the presence of MGMT promoter gene methylation, the degree of tumor resection, the patient’s age, and the location of the tumor were all taken into account by the authors." (PMID 36009577, 2022). "Distributions of tumor MGMT status and EGFR, TERT, and IDH1 genomic alterations observed in the current study are consistent with those reported in the current literature." (PMID 34510238, 2022). "MGMT methylation status from the parental tumor was available for 36 (71%) of GSC cultures, in whom nine were from recurrent tumors." (PMID 36115076, 2022). "We further compared the risk score between patients with different clinical characteristics and found that the LMG signature was associated with age, tumor grade, IDH mutation, radiotherapy, and the O-methylguanine-DNA-methyltransferase (MGMT) status." (PMID 36698888, 2022). "It should be noted that, in our series, classical prognostic parameters for GBM, such as age and MGMT status, correlated with survival; this fact supports the conclusion that it was a representative sample of this type of neoplasia." (PMID 35885058, 2022). "Our results show that the strength of MGMT promoter methylation as a predictor of survival is dependent on the abundance of cancer stem cells within the tumor." (PMID 36333778, 2022). "Our report showed that a patient with high MGMT promoter methylation status has the possibility of tumor shrinkage due to temozolomide and improvement of KPS." (PMID 35397757, 2022). "The clinical data of in the CGGA dataset included PRS type, tumor grade, age, gender, OS, radiotherapy status, chemotherapy status, IDH mutation status, MGMT methylation status, and 1p19q codeletion status." (PMID 35783014, 2022). "In T2/FLAIR images, MGMT promoter-methylated tumors were shown to have a lower hyperintense tumor volume, in contrast to unmethylated tumors." (PMID 35330402, 2022).